ANGPT2 (angiopoietin 2)
Diseases named in the same sentence as ANGPT2 in open-access papers (continued):
Sharing a sentence is not in itself a finding about the gene and the disease.
melanoma (continued). "Recently, ANGPT2 was identified as a major pro-angiogenic factor in a subset of melanomas." (PMID 35513564, 2022). "Hence, in line with our previous report, we showed the effect of ANGPT2 stimulation enhanced the capacity of TIE-2+ M-MDSC to suppress melanoma-specific T-cell function in vitro." (PMID 35935946, 2022). "Hence, we observed a profound impairment of melanoma-specific T-cell responses in patients harboring high levels of TIE-2+ M-MDSC along with ANGPT2." (PMID 35935946, 2022). "Therefore, ANGPT2 has been suggested as a predictor and prognostic marker in advanced melanoma patients treated with ICIs." (PMID 35681453, 2022). "In addition, high ANGPT2 or high VEGF‐A expression in primary melanoma predicts a lower probability of survival compared to low ANGPT2 (P = 0.0004) or VEGF‐A (P = 0.0052) expression." (PMID 34102002, 2021). "Another noteworthy up-regulated transcript up-regulated is ANGPT2, coding for angiopoietin 2 (Ang-2); Ang-2 has been identified as a metastasis inducer in melanoma as well as a bad prognosis biomarker in progress and development of colorectal cancer in Japanese and Chinese populations." (PMID 34452195, 2021). "Interestingly, the genes encoding angiopoietin-2 (ANGPT2) and interleukin-8 (IL8), two well known drivers of angiogenesis in melanoma, showed substantially higher expression (416-fold and 24-fold, respectively) in D-12 tumors than in A-07 tumors." (PMID 31915016, 2020). "Reinforcing these data, IHC and MELC staining demonstrated that tissues obtained from metastatic melanoma patients, which are known to have a worse prognosis, have higher expression levels of VEGFR‐3 and ANGPT2 compared with tissues obtained from patients with primary melanoma." (PMID 31069961, 2019). "As we observed an epigenetic regulation of Vegfc, Angpt2, and Six1 in our mouse melanoma model, we analyzed whether the promoter methylation of these genes could predict overall survival in melanoma patients by a Cox multivariate analysis." (PMID 31069961, 2019). "Furthermore, the expression of the angiogenic factor ANGPT2 and the receptor VEGFR‐3 were significantly associated with overall survival of melanoma patients." (PMID 31069961, 2019). "In malignant melanoma, soluble angiopoietin-2 (sAng-2) levels are elevated and may function as part of an autocrine Ang-2/Tie2 growth loop." (PMID 26503473, 2015). "ANGPT2 is a nearly endothelial cell-specific cytokine that promotes vascular remodeling in an autocrine pathway, and its circulating level has been reported to be in association with the progression of metastasis in melanoma patients, particularly in stage III/IV melanoma patients." (PMID 37240247, 2023). "Notably, VEGFR‐3 and ANGPT2 were previously observed to be expressed in melanoma tumor cells." (PMID 31069961, 2019). "Growth and angiogenic factors: angiopoietin-2, endoglin, fibroblast activation protein (FAP), melanoma inhibitory activity, and vascular endothelial growth factor-A (VEGF-A) were significantly (p < 0.0001) elevated in EC patients." (PMID 39511039, 2024). "This analysis revealed 15 differentially expressed proteins (including CD31, VCAM-1, ANGPT2, CXCL8, and CCL20) in the hepatic endothelial cells after co-culture with melanoma cells." (PMID 37240247, 2023). "Accordingly, a higher amount of serum ANGPT2, the ligand of TIE-2, was shown in melanoma patients and especially in advanced stages." (PMID 35935946, 2022). "Angiopoietin-2 (ANGPT2) has been proposed as a predictive and prognostic marker in ICI-treated patients with advanced melanoma." (PMID 33467713, 2021). "Meningeal A-07 melanomas showed higher expression of VEGF-A than meningeal D-12 melanomas, whereas the expression of ANGPT2 and IL8, two important angiogenesis drivers in melanoma, was much higher in D-12 than in A-07 tumors." (PMID 31915016, 2020).
melanoma (continued). "This assay confirmed the high expression of ANGPT2 and VEGFR‐3 in metastatic melanomas and showed these antigens are expressed by both the tumor and endothelial cells." (PMID 31069961, 2019). "The expression of VEGFR‐3 and ANGPT2 was also evaluated by IHC and MELC staining in primary and metastatic human melanoma tissue." (PMID 31069961, 2019). "Enhanced reduced representation bisulfite sequencing‐based methylome profiling revealed for the first time a link between abnormal VEGFC, ANGPT2, and SIX1 gene expression and promoter hypomethylation in melanoma cells." (PMID 31069961, 2019). "The methylation status of VEGFC, ANGPT2, and SIX homeobox 1 (SIX1) promoters was also found to correlate with overall survival in melanoma patients." (PMID 31069961, 2019). "To our knowledge, we are the first to show that ANGPT2 (HR = 1.189; P = 0.002) and VEGFR‐3 (HR = 1.999; P = 0.044) are independent predictors of prognosis in melanoma patients." (PMID 31069961, 2019). "Significantly elevated levels of angiopoietin-2 and soluble P-selectin (stored in WPBs adjacent to VWF) confirmed the melanoma cell supernatant-induced activation of HUVECs and the ability of Tinzaparin to inhibit EC activation." (PMID 27602496, 2016). "This was done in the B16 melanoma model, a tumor model with a strong proangiogenic phenotype, i.e. production and secretion of VEGF and angiopoietin-2." (PMID 19682397, 2009). "Interestingly, the blockade of ANGPT2 signaling increased cytotoxic CD8+ T-cell infiltration into the tumor and improved the response to immunotherapy in melanoma mouse models." (PMID 37887354, 2023). "Furthermore, using data from TCGA, they observed that the angiogenic factor ANGPT2 and the lymphangiogenic receptor VEGFR-3 can be considered independent factors to predict overall survival in patients with melanoma." (PMID 36143291, 2022). "The results were completed by analyzing Human Protein Atlas datasets, and a negative correlation was observed between ANGPT2 expression levels and overall survival in melanoma patients." (PMID 36143291, 2022). "Furthermore, analysis of The Cancer Genome Atlas data revealed that the expression of the angiogenic factor ANGPT2 (P‐value = 0.044) and the lymphangiogenic receptor VEGFR‐3 (P‐value = 0.002) were independent prognostic factors of overall survival in melanoma patients." (PMID 31069961, 2019). "Moreover, we identified VEGFR‐3 and ANGPT2 expression, as well as VEGFC, ANGPT2, and SIX1 promoter methylation, as independent prognostic factors for overall survival in melanoma patients, showing the high translational relevance of our findings obtained in a murine model." (PMID 31069961, 2019). "In addition, angiopoietin-2 was identified as an independent prognosis biomarker in myeloid leukemia and melanoma patients not treated with anti-angiogenic therapies." (PMID 24373251, 2013). "In the absence of ANGPT2, the TIE-2 inhibitors did not affect IFN-γ production by melanoma-specific T cells." (PMID 35935946, 2022).
diabetes (29 papers, 2011 to 2026). "After adjusting for age, gender, hypertension, coronary heart disease, diabetes, hyperlipidemia, smoking and alcohol history, It was found ANGPT2 level > 833 pg/ml was independently associated with type A AAD (RR = 47.297, 95%CI 16.497-135.601, p < 0.001)." (PMID 35004874, 2021). "Diabetes and low eGFR might affect the association of fluid status and circulating Angpt2 level with adverse renal outcomes." (PMID 28333979, 2017). "Surprisingly, NCS treatment reversed the diabetes-induced reduction in Angpt1 levels, although it had only a minor effect on the elevated Angpt2 levels." (PMID 39273597, 2024). "In this study, patients with both OH>1.1L and high circulating Angpt2 level were more likely to reach commencing dialysis after adjusting diabetes and baseline renal function." (PMID 28333979, 2017). "Our results found that patients with high fluid status and circulating Angpt2 level had the highest proportion of diabetes and lowest eGFR among 4 groups." (PMID 28333979, 2017). "In rats injected with streptozotocin, whole-kidney Angpt1 and Angpt2 mRNA and protein increase at 4 weeks’ diabetes duration, but after 8 weeks ANGPT1 levels diminish, while ANGPT2 remains elevated." (PMID 27207083, 2016). "After controlling for baseline variables including sex, age, dyslipidemia, hypertension, smoking status (past or current), diabetes, CAD, CHF, and prior stroke, both HGF and angiopoietin-2 plasma levels remained independently associated with the occurrence of MACE at 2 years." (PMID 40565778, 2025). "We then discuss how abnormal angiogenesis develops in eyes and kidneys under diabetes condition, focusing on “VEGF uncoupling with nitric oxide” and “competitive angiopoietin 1/angiopoietin 2” mechanisms that are shared in both organs." (PMID 27313624, 2016). "Diabetes induced an increase in immunoreactive ANGPT2 (p < 0.05) but did not alter ANGPT1, VEGFA, VEGFB, IGFBP2 or SEMA6A." (PMID 31001672, 2019). "Further adjustment for diabetes and hypertension did not substantially attenuate hazard ratios for ANGPT2, Spondin-1, TRAP5 or NOTCH1." (PMID 30557359, 2018). "In subgroup analysis, patients with both OH>1.1L and high circulating Angpt2 level had significantly increased risk for commencing dialysis independent of sex, CKD stages, diabetes and serum albumin and hsCRP levels in adjusted model." (PMID 28333979, 2017). "ANGPT2 mRNA was found to be elevated in isolated glomeruli from patients with diabetes when compared with live donor kidneys, while no change was observed in ANGPT1 expression." (PMID 27207083, 2016). "Overall, these observations are consistent with the contention that an increased ratio of ANGPT2/ANGPT1 could play a role in the development and progression of glomerular disease in diabetes." (PMID 27207083, 2016). "We measured several plasma biomarkers of endothelial cell activation (soluble E-selectin, soluble ICAM-1 and fractalkine) and barrier function (angiopoietin-1 and angiopoietin-2), neither of which was modified in patients with diabetes mellitus." (PMID 27495247, 2016). "Multiple regression analysis showed that vitreous ANGPT2 concentrations were not independently associated with CST in ERM patients with ME when controlling for age, sex, ethnicity, body-mass index (BMI), diabetes, cardiovascular disease and phakic status (results not shown)." (PMID 28878218, 2017). "Parallel work from our group has shown that, in the very early stages of diabetic glomerulopathy (3 weeks’ diabetes duration), glomerular Angpt1 mRNA decreases in diabetic mice, with no significant changes in Angpt2 mRNA levels, when compared with non-diabetic animals." (PMID 27207083, 2016). "A report of similar design to ours with diabetes and unstable angina pectoris (UAP) found no changes in angiogenic factors in diabetes alone, but increased VEGF and angiopoietin-2 in UAP." (PMID 35996503, 2022).
hepatocellular carcinoma (26 papers, 2015 to 2025). A malignant tumor that arises from hepatocytes. "High serum levels of angiopoietin-2 have previously been associated with severity of hepatocellular carcinoma, colorectal cancer and metastatic melanoma." (PMID 39511039, 2024). "sAng-2 was elevated in patients with hepatocellular carcinoma, suggesting the potential use of angiopoietin-2 as a valuable diagnostic biomarker for the detection of hepatocellular carcinoma (Bouattour, Payance & Wassermann, 2015)." (PMID 28584715, 2017). "For instance, transcriptional analysis of tumor-associated MAIT cells in hepatocellular carcinoma indicated upregulation of ANGPT2 (encoding for angiopoietin-2) that may suggest proangiogenic functions." (PMID 34298791, 2021). "As for ANGPT2 rs3020221, it is an sSNP in exon 4 with potential phenotypic consequences and, similarly to our findings, the C allele was associated with poor OS in hepatocellular carcinoma in the single published study." (PMID 32526933, 2020). "Several studies have shown that ANGPT2 gene variants are associated with the course and effects of treatment for colorectal cancer, lung cancer, head and neck squamous cell carcinoma, hepatocellular carcinoma and diseases other than cancer, such as rheumatoid arthritis and systemic sclerosis." (PMID 40115011, 2025). "Increased ANGPT2 expression has also been described as a potential prognostic factor in colorectal carcinoma, gastric cancer, hepatocellular cancer, lung cancer, and chronic lymphocytic leukemia." (PMID 40115011, 2025). "In hepatocellular carcinoma, ARID1A deficiency promotes angiopoietin-2-induced angiogenesis that correlates with the cancer progression and aggressiveness." (PMID 35069887, 2022). "Angiopoietin-1 (Ang-1) and angiopoietin-2 (Ang-2) play critical roles in angiogenesis in hepatocellular carcinoma (HCC)." (PMID 30701027, 2018). "In addition, serum neuropilin-1 and angiopoietin-2 are potential markers for hepatocellular carcinoma diagnosis." (PMID 34656128, 2021). "Other reports indicate that hepatic stellate cells, tissue-specific pericytes in the liver, overexpress FAP following activation and promote angiogenesis in liver fibrosis and hepatocellular carcinoma by increasing the levels of Angiopoietin-1 and Angiopoietin-2." (PMID 34282761, 2021). "Moreover, the same study showed that angiopoietin-1 and angiopoietin-2 can be detected in hepatoma cells, HSCs, and smooth muscle cells." (PMID 30959975, 2019). "Noninvasive evaluation of the expression of angiopoietin-2 (Ang-2) and transketolase (TKT) in hepatocellular carcinoma (HCC) is of great significance for the clinical development of individualized treatment plans." (PMID 33520706, 2020). "Studies have confirmed that in Hepatocellular Carcinoma (HCC), AMYB proto-oncogene-like 1(MYBL1) binds to the ANGPT2 promoter and upregulates ANGPT2 mRNA expression." (PMID 40061897, 2025). "Studies in hepatocellular carcinoma also showed that transcriptional expression of the Angpt2 promoter was directly targeted by FOXC2 and that Angpt2 knockdown abolished FOXC2-facilitated angiogenesis and tumor growth, suggesting that FOXC2 promotes tumor progression via regulation of Angpt2." (PMID 36230774, 2022).
malaria (26 papers, 2009 to 2025). Malaria is a serious and sometimes fatal disease caused by a parasite that commonly infects a certain type of mosquito which feeds on humans. "In knowlesi malaria, CFHb was associated with parasitaemia, and independently associated with angiopoietin-2 and osteoprotegerin." (PMID 29872039, 2018). "The level of angiopoietin-2, another marker of malaria severity, was associated with increasing BH2 (r = 0.44, p = 0.02), but was not significant after adjusting for disease severity." (PMID 25764397, 2015). "In human CM, high levels of angiopoietin-2 and low levels of angiopoietin-1 are linked to CM severity and studies suggest these angiogenic factors function as prognostic biomarkers that can discriminate severe CM from mild malaria and predict fatal CM outcome." (PMID 24433482, 2014). "The plasma concentrations of the biomarkers for endothelial activation, such as the von Willebrand factor (vWF) and angiopoietin-2 (ANG-2), are markedly elevated in severe malaria and have been associated with both the severity and mortality of the illness." (PMID 37375081, 2023). "Elevated plasma angiopoietin-2 and soluble ICAM-1 are two markers of endothelium activation and increased permeability that were previously associated with malaria severity and risk of cognitive impairment." (PMID 36759905, 2023). "In knowlesi malaria, there is also significant correlation with biomarkers of endothelial activation [angiopoietin-2 and osteoprotegerin (OPG)] and measures of microvascular function." (PMID 34858979, 2021). "In knowlesi malaria, plasma syndecan-1 was also highest in those with severe disease, and correlated with markers of endothelial activation (angiopoietin-2, osteoprotegerin, ICAM-1), asymmetric dimethylarginine (ADMA) and impaired microvascular reactivity." (PMID 33963210, 2021). "Angiopoietin-1 and Angiopoietin-2 concentrations were measured in peripheral and placental plasma samples from 70 malaria-infected and 216 control women using commercially available DuoSet ELISA development kit." (PMID 32399088, 2020). "In this study we found that OPG and angiopoietin-2 were both independently associated with AKI, suggesting that haemolysis-induced endothelial activation is an important mechanism of malaria-associated AKI." (PMID 29872039, 2018). "Angiopoietin-2 levels were significantly higher in those with malaria; SM with CM patients had levels higher than those with MSM, and levels in CM patients were higher than those with SM without CM." (PMID 27385484, 2016). "Among patients with malaria, arginase activity significantly correlated with angiopoietin-2, lactate, arginine, and the arginine/ADMA ratio." (PMID 27385484, 2016). "High levels of angiopoietin-1 are associated with endothelial stability and aberrant angiopoietin-1 and angiopoietin-2 levels have been proposed as good biomarkers for severe malaria." (PMID 24995009, 2014). "Plasma concentrations of angiopoietin-2 (Ang-2), an angiogenic factor stored in WPBs, predict increased mortality in malaria, and ICAM-1 is a major endothelial adhesion receptor mediating cytoadherence of parasitized red cells and microvascular sequestration." (PMID 20421938, 2010). "The findings in our study suggest that in addition to the role of angiopoietin-2 in mediating glycocalxy breakdown in malaria, agents that increase heparanase expression such as ADMA and OPG may also contribute." (PMID 33963210, 2021). "Elevated angiopoietin-2 (Angpt-2) concentrations are associated with worse overall neurocognitive function in severe malaria survivors, but the specific domains affected have not been elucidated." (PMID 33407493, 2021). "Indeed, the ratio of angiopoietin-1 to angiopoietin-2 has been proposed as a potential marker of severe malaria with prognostic value." (PMID 30249265, 2018).